NRAS (NRAS proto-oncogene, GTPase)
Diseases named in the same sentence as NRAS in open-access papers (continued):
Sharing a sentence is not in itself a finding about the gene and the disease.
melanoma (continued). "However, only recently has the association between NRAS mutant melanomas and autophagy inhibition matured despite the existence of a clinical trial in progress exploring the combination of MEK pathway modulators and autophagy inhibitors (NCT03979651)." (PMID 34885944, 2021). "In melanomas, only NRAS is exclusively mutated in about 15–20% of patients." (PMID 34063141, 2021). "Some studies mentioned that NRAS mutation seemed to be a poor prognosis in leptomeningeal melanosis and melanomas because of the activation of both ERK and the phosphatidylinositol 3-kinase (PI3K)/AKT pathway, in contrast to ERK signaling alone in BRAF mutation cases." (PMID 34063325, 2021). "However, results from an Asian multicenter phase II trial of toripalimab in advanced melanoma patients indicated NRAS mutation as a potential resistance mechanism for immunotherapy." (PMID 34290710, 2021). "About 20–30% of melanomas harbor NRAS mutations, which are also able to activate the MAPK pathway." (PMID 35008245, 2021). "Interestingly, PTEN gene alterations are mutually exclusive with NRAS mutations, and approximately 20% of melanomas with loss of PTEN function also have BRAFV600E mutations." (PMID 34571969, 2021). "A novel RAF inhibitor, LXH254—which may have activity in tumors with concurrent BRAF and NRAS mutations, and in melanoma cell lines that are resistant to BRAF and MEK inhibition—was found to be less active in the KRAS mutant cell lines." (PMID 34830283, 2021). "The cytoplasmic intergenic lncRNA MIRAT (MAPK inhibitor resistance-associated transcript), instead, has been described as significantly over-expressed in melanoma cells, carrying NRAS or BRAF mutations, resistant to small molecule inhibitors of the MAPK cascade." (PMID 33503876, 2021). "Hyperactive MAPK signaling is also caused by mutations of NRAS (about 20% of malignant melanoma)." (PMID 34576054, 2021). "Typically, either BRAF or NRAS mutations are found in malignant melanomas." (PMID 34576054, 2021). "Interestingly, melanomas harboring NF1 or NRAS mutation are associated with higher TMB compared with other phenotypes, opening the opportunity to use immunotherapy with more solid scientific support." (PMID 35008245, 2021). "The lack of discrimination between BRAF-mt and BRAF-wt melanoma could potentially be explained by activating mutations in the NRAS gene in BRAF-wt melanoma." (PMID 33915880, 2021). "Mucosal melanomas show a lower frequency of NRAS Q61 mutations and a higher frequency of mutations in G12 and G13, suggesting that these are not linked to UV irradiation but possibly due to the effect of external genotoxic factors, which remain to be identified." (PMID 35008570, 2021). "The prognostic impact of NRAS mutations in melanomas is controversial." (PMID 34831002, 2021). "About 15% of melanomas contain NRAS (neuroblastoma rat sarcoma viral oncogene) mutations." (PMID 34063141, 2021). "In fact, NRAS mutation is even higher in Caucasian patients with melanomas." (PMID 34063325, 2021). "Notably, in other works, this negative regulation of NRAS expression by miR-145 has been associated with inhibition of proliferation, invasion, and migration of melanoma cells." (PMID 33916029, 2021). "Eighteen (40%) patients had a BRAF-mutated and 8 (18%) had an NRAS-mutated melanoma." (PMID 34073477, 2021). "Melanomas that harbor NRAS mutation, either previously untreated and those progressed on immunotherapy, might be targeted by MEK inhibitor such as Binimetinib or Pimasertib." (PMID 34571863, 2021). "Furthermore, it has been demonstrated that melanomas develop resistance to these inhibitors due to secondary mutations in V-Ras neuroblastoma RAS viral oncogene homolog (NRAS) and other mutational alterations." (PMID 34680938, 2021). "NRAS mutations have been observed in melanoma, which suggests that UV radiation may play a significant role in introducing these mutations." (PMID 34441278, 2021).
melanoma (continued). "NRAS mutations account for 26% of all mutations present in melanomas registered in TCGA." (PMID 34831002, 2021). "Additionally, the correlation between histopathological subtypes of BRAF/NRAS-mutated melanoma and PLA1A was analyzed." (PMID 33723350, 2021). "We recently showed in another study that the lack of detection of ctDNA by qPCR Cobas (Roche diagnostics) at the initiation of first-line treatment was an independent factor of good prognosis, regardless of treatment (immunotherapy or targeted therapy) in BRAF or NRAS-mutated melanoma patients." (PMID 33920470, 2021). "In light of the relatively high mutation rate of KIT in cutaneous melanoma and since BRAF, KIT, and NRAS mutations appear to be mutually exclusive, the screening of KIT mutations, at least in exons 9/11/13, is suggested in BRAF/NRAS double-wild-type melanoma patients." (PMID 34123788, 2021). "The Q16R mutation is the most common NRAS mutation in melanoma." (PMID 34203771, 2021). "Moreover, BRAF-mutated melanomas are more common in younger patients whereas NRAS mutations are encountered in older patients and in the nodular histological subtype." (PMID 34123788, 2021). "Overall survival was significantly correlated with increased age (r = 0.25, p < 0.10), and was significantly higher in patients with melanoma at stage M1a stage, NRAS mutation, better ECOG performance status, an LDH below the ULN, and fewer than three metastatic sites." (PMID 33669266, 2021). "However, they did not observe any specific differentially expressed miRNAs between BRAF- and NRAS-mutated melanomas." (PMID 34123788, 2021). "In addition, a subset of melanomas with IDH1 mutations that are significantly associated with co-existing NRAS mutations has been described." (PMID 34205480, 2021). "This represented a pivotal mechanism of resistance in NRAS-mutated melanomas." (PMID 34063141, 2021). "Recently, new reports tried to assess the existence of any correlation between mutations in the main genes (BRAF/NRAS) involved in melanoma initiation and progression; they have proposed a distinct molecular classification for MUP to explain the differences in patient outcomes." (PMID 33747946, 2021). "NRAS mutations are the second most frequent mutations in malignant melanoma." (PMID 34069297, 2021). "While the major drivers of melanoma initiation, including activation of NRAS/BRAF and loss of PTEN or CDKN2A, have been identified, the role of key transcription factors that impose altered transcriptional states in response to deregulated signaling is not well understood." (PMID 34140478, 2021). "Therefore, the diagnostic value of PLA1A in BRAF and NRAS-mutated samples of melanoma patients was investigated to confirm the diagnostic utility of PLA1A during melanomagenesis." (PMID 33723350, 2021). "Moreover, this miRNA has been shown to target one of the most recurrently mutated genes in melanoma i.e., the NRAS gene." (PMID 33968718, 2021). "Although BRAF and NRAS mutations are usually mutually exclusive in melanoma patients, BRAF/NRAS dual mutation may derive from two subclonal populations." (PMID 34675197, 2021). "In addition, it was recently observed that melanoma CIMP associated with an NRAS-mutant phenotype is more aggressive than melanoma CIMP associated with BRAF-mutant melanoma." (PMID 34944843, 2021). "These two mutations (BRAF and NRAS) are the most common genetic alterations in human melanoma." (PMID 33937086, 2021). "Whether the acquisition of an NRAS or IDH1 mutation in an atypical DPN may represent a molecular evolution implying a pathway to melanoma progression should be confirmed in a larger series." (PMID 34205480, 2021). "In comparison with wild-type melanoma, NRAS mutations may result in a significantly worse melanoma-specific survival rate." (PMID 34441278, 2021). "Therefore, binimetinib (used also in BRAFi-resistant melanomas) has been used for the treatment of NRAS-mutated melanomas either alone or in combination with encorafenib." (PMID 34063141, 2021).
melanoma (continued). "It is a valuable UV-independent genetic model for the development of melanoma, with causative somatic pathogenic variants in NRAS in 70%,2,3 and BRAF in 7%,3,4 with the remainder as yet unknown." (PMID 34145395, 2021). "However, we have shown co-occurrence of mGluR1 expression and mutated NRAS in human melanoma cell lines and patient biopsies." (PMID 34359771, 2021). "NRAS is the second most common mutated oncogenic driver in melanoma, after BRAF mutations." (PMID 35187538, 2021). "In addition, a patient in which melanoma arose from a congenital nevus was positive for an NRAS mutation." (PMID 33996584, 2021). "Additionally, NRAS mutations are found in 15–30% of melanoma patients, and NF1 mutations are found in 12–18% of all melanomas." (PMID 34066966, 2021). "Additionally, the combination of CDK4 and MAPK pathway inhibitors has shown tumor regression in xenograft models of cancers with KRAS, NRAS, or BRAF mutations, particularly BRAF- and NRAS-mutant melanoma, with promising results from phase I clinical studies." (PMID 34309585, 2021). "In the TCGA database, 111 melanoma samples were tested for NRAS mutations." (PMID 34698264, 2021). "However, in recent years, MEK inhibition was shown to demonstrate therapeutic activity in NRAS-mutated melanoma in clinical trials, opening a novel therapeutic era for these tumors." (PMID 34102999, 2021). "However, we identified six KRAS mutations and one NRAS mutation in 19 melanomas of the female genital tract." (PMID 34102999, 2021). "As NRAS mutated melanoma tumors may show aberrant c-Met activation contributing to their aggressive nature, PHA-66752 was tested in this subgroup." (PMID 33918490, 2021). "In an NRAS mutation model of melanoma, PHGDH was found to be upregulated." (PMID 33511334, 2020). "The second-largest group of melanoma patients bears activating mutations in the NRAS protein." (PMID 32531927, 2020). "NRAS activating mutations are present in approximately 15–20% of melanomas." (PMID 32092958, 2020). "Eighteen patients (30%) had BRAF WT melanoma, among whom 13 were NRAS-mutated." (PMID 32585901, 2020). "A total of 32 patients had a BRAF-mutated melanoma and 36 had an NRAS mutation." (PMID 32664549, 2020). "For example, PREX2 GEF activity was activated by mutations found in NRAS-mutant melanoma." (PMID 31906480, 2020). "In this context, it would be important to clarify the role of these mutations in the prognosis of melanoma patients by staging to understand whether NRAS mutations could be important biomarkers to predict the behavior of this disease." (PMID 33072757, 2020). "Although it can be difficult to target a promoter variant, TERT silencing has been successful in NRAS mutant melanoma and might be applied to other tumors in the future." (PMID 32455687, 2020). "Most frequent mutations are found in BRAF (40–60% of melanoma patients) and NRAS (15–20%)." (PMID 31659567, 2020). "Importantly, a very similar shift in the mTOR subcellular localization was also observed in two human melanoma cell lines expressing mutated NRAS, MEL-JUSO and SK-MEL-30." (PMID 32531927, 2020). "Of the 54 melanoma samples analyzed, 38.8% had NRAS mutations." (PMID 32775409, 2020). "Several studies showed that NRAS mutations may result in an inferior clinical outcome with a shorter Melanoma-Specific Survival (MSS), although partially debated." (PMID 32850962, 2020). "Interestingly, TYRP1 mRNA levels in cells carrying mutation either in NRAS or in HRAS were much higher than in BRAFV600E melanoma cells." (PMID 31624899, 2020). "NF1 mutations are present in <15% of melanoma cases and may be present together with NRAS/BRAF mutations." (PMID 32054078, 2020).
melanoma (continued). "This is a retrospective analysis that included 161 patients with BRAF V600E or neuroblastoma RAS viral oncogene homolog (NRAS) pQ61L/K mutated melanoma in primary tumor and in which the presence of the same mutations in ctDNA was analyzed within 12 weeks after surgery using dPCR." (PMID 32629823, 2020). "Thus, agents that repress the eIF4E-eIF4G interaction hold the promise of inhibiting high-risk melanomas that are inherently drug resistant, such as NRAS-mutant melanomas, or those with acquired resistance to therapy." (PMID 32517051, 2020). "Indeed, 28% of all melanoma cases have mutations in the NRAS gene, being after BRAF mutations the second most frequent oncogenic alteration in this type of cancer." (PMID 33072757, 2020). "Also on a molecular level, NM seems to be a distinct melanoma subtype, because it is more frequently associated with NRAS mutations than SSM, and it has been shown that this mutation is associated with progressive disease." (PMID 33409460, 2020). "Since the MAPK pathway is frequently activated in melanoma via mutation of BRAF or NRAS and p300 acetyl transferase activity is enhanced by MAPK-mediated phosphorylation in keratinocytes, we asked whether MAPK signaling activates acetylation in melanoma." (PMID 32531202, 2020). "The inhibition of this enzyme using selective COX-2 inhibitors in BRAF- or NRAS-mutated melanoma may represent a reasonable and clinically feasible option to help inhibit tumor progression and induce tumor cell death." (PMID 32296574, 2020). "The palms and soles sites of the melanoma may contribute to the higher frequency, as higher frequencies of NRAS mutations were found in melanomas on the palms and soles rather than on the dorsal acral sites." (PMID 32083130, 2020). "Thus, NRAS mutational analysis should be included in melanoma routine diagnosis, given its relevance as a biomarker of melanoma aggressiveness and easy evaluation." (PMID 33072757, 2020). "NRAS p.Q61R was the more frequent NRAS mutation (12.8% of mutated melanoma samples)." (PMID 32340363, 2020). "Activating mutations of BRAF and NRAS are the most common mutations observed in melanoma." (PMID 32196516, 2020). "Here, we investigated the influence of different melanoma-associated NRAS mutations (codon 12, 13 or 61) on several parameters such as oncogene-induced senescence, cell proliferation, migration or colony formation in immortalized melanocytes and in melanoma cell lines." (PMID 31906480, 2020). "However, as NF1 mutations can be found in melanomas with concurrent BRAF or NRAS hotspot mutation, a three-group classification of melanoma (mutant BRAF, mutant RAS, non-BRAFmut /non-NRASmut) has been proposed." (PMID 32850962, 2020). "To assess whether the prognostic classifier was an independent indicator in distinct subgroups, we checked the effect of BRAF and NRAS mutation or wild-type on the prognostic ability for melanoma in TCGA cohort." (PMID 33005180, 2020). "Melanoma patients carrying an oncogenic NRAS mutation represent 20% of all cases and present worse survival, relapse rate and therapy response than patients with wild type NRAS or with BRAF mutations." (PMID 31906480, 2020). "Ribociclib also showed some activity in melanomas with activating mutations of BRAF or NRAS." (PMID 32850962, 2020). "To reiterate, evaluation of the activity of OXPHOS complexes showed higher levels in BRAF-mutated and BRAF/NRAS wild-type melanoma cell lines compared to HDFs, most likely due to a higher mitochondrial mass as indicated by VDAC1 immunostaining and activity of citrate synthase." (PMID 33007949, 2020).
melanoma (continued). "(2019) on effects of this mutation on NRAS activation and melanoma progression may need to be reconsidered." (PMID 32531245, 2020). "Treatment with a MEK inhibitor (MEKi) was disappointing, where phase 3 NEMO study showed a modest increase of PFS with binimetinib (2.8 months) versus dacarbazine (1.7 months) in NRAS-mutated advanced melanoma such that MEKi is rarely used as a valuable option in this setting." (PMID 32585901, 2020). "Overall, the imminent role of NRAS mutations in melanoma aggressiveness and response to therapy has been well established, although much is still to discover about the impact of the remaining Ras family members in melanoma pathophysiology and as putative therapeutic targets." (PMID 33072757, 2020). "The overall objective of our studies is to better understand the underlying pathophysiology which could explain the well-established exclusivity between BRAF(V600E) and NRAS(Q61) mutations in melanoma." (PMID 30651601, 2019). "Finally, a major unmet issue in melanoma is targeting mutated forms of NRAS kinases, which are still considered undruggable." (PMID 31861757, 2019). "The most common somatic mutations are activating point mutations in the v-Raf murine sarcoma viral oncogene homolog (BRAF; 35–50% of melanomas) and neuroblastoma RAS viral oncogene homolog (NRAS; 10–25%), as well as loss-of-function mutations affecting neurofibromin 1 (NF1; ~15%)." (PMID 31470659, 2019). "Some scientists have struggled to find drugs targeting the mutated NRAS protein or NRAS protein, while others have uncovered a mechanism of resistance of targeted therapies for melanoma and identified compounds that inhibit eIF4F and enhance the effectiveness of vemurafenib in mice with melanomas." (PMID 30925905, 2019). "TERT promoter mutations have been shown to correlate with poorer outcomes in subsets of melanoma patients with BRAF/NRAS mutations, and this may serve as a potential future biomarker." (PMID 31861163, 2019). "Importantly, the RAC1 P29S mutation was more frequent in melanomas that were wild type for both NRAS and BRAF." (PMID 31027363, 2019). "Strikingly, the BRAF and NRAS mutation profiles in mucosal melanoma are closer to those found in cancers such as lung cancer, suggesting that mutations in mucosal melanoma could be linked to some genotoxic agents that remain to be identified." (PMID 31398831, 2019). "Binimetinib was the first targeted therapy to show activity in patients with NRAS-mutated melanoma." (PMID 30956763, 2019). "Along these lines, we set out to more deeply characterize the mechanism(s) which proscribe the concurrence of BRAF(pV600E) and NRAS(pQ61) mutations in melanoma with an eye towards novel pathways which could countermand constitutive BRAF or NRAS signaling." (PMID 30651601, 2019). "Notably, BRAF mutations are quite infrequent in mucosal melanomas (5% of cases, compared to 15% of NRAS and 26% of c-KIT mutations)." (PMID 30934534, 2019). "In addition, serine threonine kinase STK19, which phosphorylates and thereby activates NRAS, has been shown to be recurrently mutated in melanomas in an earlier study." (PMID 30987166, 2019). "We found a co-occurrence of IDH1 with NRAS mutations in 3/5 primary melanomas." (PMID 31745173, 2019). "In agreement with this hypothesis, it was reported that, in the p16INK4a-deficient mouse melanoma model, the frequency of metastatic melanoma initiation by NRAS Q61R was increased more than 20-fold, compared with NRAS G12D." (PMID 31398831, 2019). "Furthermore, hTERT promoter mutations are also closely associated with FGFR3 mutations in BC, or with BRAF/NRAS mutations in melanoma or papillary thyroid carcinoma (PTC)." (PMID 31186051, 2019). "Binimetinib showed activity in patients with BRAF- or NRAS-mutated melanoma through MAPK pathway inhibition, and genomic profiling highlighted genetic alterations of interest that could be used as potential predictive biomarkers of response to binimetinib." (PMID 30956763, 2019).